TMEM178A (transmembrane protein 178A)
Description:
Acts as a negative regulator of osteoclast differentiation in basal and inflammatory conditions by regulating TNFSF11-induced Ca (2+) fluxes, thereby controlling the induction of NFATC1.
Synonyms: TMEM178; MGC33926
Tractability: Antibody: UniProt predicts a signal peptide or a membrane-spanning region.
Gene: Protein-coding gene on chromosome 2 (39,664,982 to 39,717,963, forward strand). Ensembl gene ENSG00000152154.
Subcellular location: Endoplasmic reticulum membrane
Subcellular location (Human Protein Atlas): Vesicles; Nucleoplasm
Gene Ontology:
Molecular function: protein binding
Biological process: negative regulation of osteoclast differentiation; regulation of cytosolic calcium ion concentration
Cellular component: endoplasmic reticulum membrane; membrane
Genetic constraint (gnomAD): Loss-of-function variants: 12 observed, 22.88 expected, observed/expected ratio (o/e) 0.52, 90% interval 0.34 to 0.85. The synonymous counts are far from expectation, so gnomAD's model fits this gene poorly and the ratio says little. Missense variants: 366 observed, 340.82 expected, observed/expected ratio (o/e) 1.07, 90% interval 0.99 to 1.17. Synonymous variants: 210 observed, 155.01 expected, observed/expected ratio (o/e) 1.35, 90% interval 1.21 to 1.52.
Homologues: Orthologues: chimpanzee TMEM178A (100% identical), macaque TMEM178A (100% identical), dog TMEM178A (99% identical), rabbit TMEM178A (99% identical), pig TMEM178A (99% identical), mouse Tmem178 (98% identical), rat Tmem178a (98% identical), tropical clawed frog tmem178a (79% identical), zebrafish tmem178a (71% identical), guinea pig TMEM178A (59% identical). Paralogues in human: TMEM178B (46% identical).
Diseases named in the same sentence as TMEM178A in open-access papers:
TMEM178A is named in the same sentence as 6 diseases in open-access papers, as found by Europe PMC text mining. Sharing a sentence is not in itself a finding about the gene and the disease.
TMEM178A shares sentences with these, for which no sentence is quoted: asthma (2 papers); tumor (2); metastatic melanoma (1); pancreatic cancer (1); pituitary adenomas (1); prostate carcinoma (1).